AKR1B15 (aldo-keto reductase family 1 member B15)
Description:
[Isoform 1]: Catalyzes the NADPH-dependent reduction of a variety of carbonyl substrates, like aromatic aldehydes, alkenals, ketones and alpha-dicarbonyl compounds. In addition, catalyzes the reduction of androgens and estrogens with high positional selectivity (shows 17-beta-hydroxysteroid dehydrogenase activity) as well as 3-keto-acyl-CoAs. Displays strong enzymatic activity toward all-trans-retinal and 9-cis-retinal. May play a physiological role in retinoid metabolism. [Isoform 2]: No oxidoreductase activity observed with the tested substrates.
Synonyms: AKR1B10L; AKR1B10L, AK1R1B7; AKR1R1B7
Tractability: Antibody: the Human Protein Atlas places it where antibodies can reach. PROTAC: ubiquitination databases record sites on it.
Gene: Protein-coding gene on chromosome 7 (134,549,110 to 134,579,875, forward strand). Ensembl gene ENSG00000227471.
Subcellular location: Mitochondrion (Isoform 1); Cytoplasm, cytosol (Isoform 2)
Subcellular location (Human Protein Atlas): Cytosol; Plasma membrane
Pathways (Reactome):
Metabolism: Estrogen biosynthesis
Gene Ontology:
Molecular function: all-trans-retinol dehydrogenase (NADP+) activity; allyl-alcohol dehydrogenase activity; estradiol 17-beta-dehydrogenase [NAD(P)+] activity; farnesol dehydrogenase activity; protein binding; testosterone dehydrogenase (NADP+) activity; aldose reductase (NADPH) activity; 17-beta-hydroxysteroid dehydrogenase (NADP+) activity; alcohol dehydrogenase (NADP+) activity; carbonyl reductase (NADPH) activity; oxidoreductase activity; oxidoreductase activity, acting on the CH-OH group of donors, NAD or NADP as acceptor
Biological process: estrogen biosynthetic process; lipid metabolic process; retinol metabolic process
Cellular component: cytosol; mitochondrion; plasma membrane; mitochondrial matrix
Genetic constraint (gnomAD): Loss-of-function variants: 44 observed, 37.04 expected, observed/expected ratio (o/e) 1.19, 90% interval 0.93 to 1.53. The upper end of that interval is the gene's LOEUF score, 1.53, which puts it in group 6 of 6, group 1 being the genes least tolerant of losing a copy. Missense variants: 362 observed, 358.16 expected, observed/expected ratio (o/e) 1.01, 90% interval 0.93 to 1.1. Synonymous variants: 125 observed, 123.1 expected, observed/expected ratio (o/e) 1.02, 90% interval 0.88 to 1.18.
Homologues: Orthologues: chimpanzee AKR1B15 (99% identical), zebrafish akr1a1a (45% identical), zebrafish zgc:56622 (39% identical), Drosophila melanogaster CG12766 (39% identical), Drosophila melanogaster CG6083 (38% identical), Caenorhabditis elegans Y39G8B.1 (38% identical), Drosophila melanogaster CG10863 (38% identical), Drosophila melanogaster CG10638 (36% identical), Drosophila melanogaster ARY (35% identical), Drosophila melanogaster CG9436 (32% identical), Caenorhabditis elegans C07D8.6 (31% identical), Caenorhabditis elegans Y39G8B.2 (29% identical), and 14 more. Paralogues in human: AKR1B10 (79% identical), AKR1B1 (60% identical), AKR1E2 (51% identical), AKR1D1 (44% identical), AKR1C4 (43% identical), AKR1C2 (43% identical), AKR1C1 (42% identical), AKR1C8 (42% identical), AKR1C3 (42% identical), AKR1A1 (41% identical), KCNAB1 (22% identical), KCNAB2 (22% identical), and 4 more.
Diseases named in the same sentence as AKR1B15 in open-access papers:
AKR1B15 is named in the same sentence as 5 diseases in open-access papers, as found by Europe PMC text mining. Sharing a sentence is not in itself a finding about the gene and the disease. The quoted sentences say what the papers report.
Insulin resistance (1 paper, 2019). Increased resistance towards insulin, that is, diminished effectiveness of insulin in reducing blood glucose levels. "Dehydrogenase/reductase member 11 (DHRS11) and AKR1B15 are novel biomarkers for the development of insulin resistance." (PMID 30678306, 2019).
liver cancer (1 paper, 2025). An epithelial or non-epithelial malignant neoplasm that arises from the liver. "Notably, in our scRNA-seq expression analysis, AKR1B15 was expressed exclusively in liver cancer tissues and not in macrophages." (PMID 40377731, 2025).
psoriasis (1 paper, 2017). An autoimmune condition characterized by red, well-delineated plaques with silvery scales that are usually on the extensor surfaces and scalp. "Notably, AKR1B10, AKR1B15, and several members of the PLA2 gene family were significantly overexpressed in psoriasis lesion tissue." (PMID 29204449, 2017).
cancer (4 papers, 2015 to 2025). A tumor composed of atypical neoplastic, often pleomorphic cells that invade other tissues. "While AKR1B10 is a well characterized enzyme with high retinaldehyde reductase activity, involved in the development of several cancer types, the enzymatic activity and physiological role of AKR1B15 are still poorly known." (PMID 26222439, 2015). "There are very few reports on the involvement of AKR1B15 in cancer." (PMID 39055885, 2024). "More research on the role of AKR1B15 in different types of cancer is warranted." (PMID 39055885, 2024). "For example, AKR1B15, COL17A1, CRABP1, and ITPRID1 were downregulated in BRCA, COAD, and PRAD but upregulated in LUAD, highlighting their cancer type-specific regulatory behavior." (PMID 41439026, 2025). "Given this evidence, further research is needed to investigate the role of AKR1B15, MTATP8P1, and SP6 in cancer." (PMID 38086955, 2023). "However, there is currently no research on the role of AKR1B15, MTATP8P1, and SP6 in cancer." (PMID 38086955, 2023).
AKR1B15 also shares sentences with these, for which no sentence is quoted: Obesity (1 paper).